MDM2 (MDM2 proto-oncogene)
Diseases named in the same sentence as MDM2 in open-access papers (continued):
Sharing a sentence is not in itself a finding about the gene and the disease.
liposarcoma (continued). "Treatment of dedifferentiated liposarcoma cell lines with romidepsin reduced tumor growth and decreased mouse double minute 2 (MDM2) expression." (PMID 36968022, 2023). "In well-differentiated and dedifferentiated liposarcoma, the amplification of 12q13-15 is common, resulting in the amplification of the MDM2 gene." (PMID 37240900, 2023). "For example, MDM2 overexpression has been observed in particular in liposarcomas, which are a type of soft-tissue tumor that arises from fat cells." (PMID 37297833, 2023). "Well differentiated liposarcoma (WDLPS) takes the largest part of liposarcoma with the characteristics of local aggressiveness and amplification of the MDM2 gene." (PMID 35392952, 2022). "For example, presence of MDM2 protein expression and/or MDM2 gene amplifications confirm the diagnosis of dedifferentiated liposarcoma." (PMID 35001360, 2022). "MDM2 antibodies can aid with well-differentiated liposarcoma/atypical lipomatous tumour and dedifferentiated liposarcoma, although MDM2 amplification is suggested in unclear cases." (PMID 36176865, 2022). "Liposarcomas were positive for CDK4 and MDM2 immunohistochemical stains, and the only case tested was found to harbor CDK4 and MDM2 mutations." (PMID 35001360, 2022). "The main genetic characteristic of liposarcoma is amplification of the MDM2 gene located on chromosome 12q13‐15, detectable by FISH." (PMID 36043432, 2022). "For example, the most common molecular tests for MDM2 and CDK4 mutations were used to dedifferentiated liposarcoma and undifferentiated pleomorphic sarcoma, and both entities are treated identically." (PMID 35115589, 2022). "The tumor showed MDM2 gene amplification, and eventually was categorized as well-differentiated liposarcoma." (PMID 34089125, 2022). "The diagnosis was confirmed with immunostaining for S-100, SOX10, and MDM2, which excluded tumors originating from the neural crest and liposarcoma." (PMID 35954639, 2022). "The most commonly investigated gene products were MDM2 and CDK442,43, the mutations of which are markers for liposarcoma." (PMID 35115589, 2022). "FISH for MDM2 amplification has also been used in cases with differential diagnoses of dedifferentiated liposarcoma and undifferentiated pleomorphic sarcoma." (PMID 36164527, 2022). "RG7112 was the first MDM2 inhibitor clinically assessed in a trial registered with EudraCT (2009-015522-10) in patients with MDM2-amplified liposarcomas." (PMID 34911439, 2021). "Several molecular targeted therapies exist for other subtypes, including CDK4 inhibitors and MDM2 inhibitors for well-differentiated liposarcoma and dedifferentiated liposarcoma, and trabectedin for myxoid liposarcoma." (PMID 34797454, 2021). "One of the molecular hallmarks of dedifferentiated liposarcoma is high levels of MDM2 DNA, a finding observed in nearly all DDLPS tumors." (PMID 33643547, 2021).
liposarcoma (continued). "Two studies reviewing the clinical-pathological and molecular features of esophageal lipoma and liposarcoma found MDM2 amplification by fluorescence in situ hybridization in all cases, with some of these patients presenting recurrent disease." (PMID 33026474, 2021). "Well-differentiated and dedifferentiated liposarcoma (WD- and DD-LPS) are two subtypes of LPS that are genetically related through an amplification of the oncogene murine double minute 2 (MDM2)." (PMID 33799327, 2021). "MDM2 and TERT amplifications have been associated with chromothripsis in liposarcoma, while EGFR, MDM2 and loss of CDKN2A in glioblastoma." (PMID 34245122, 2021). "MDM2 amplification has been well documented in well-differentiated liposarcomas/atypical lipomatous tumors, intimal sarcomas, and hematologic malignancies." (PMID 35049602, 2021). "The recurrent large lipomatous tumor was confirmed as well-differentiated liposarcomas through histological and MDM2-FISH immunohistochemical staining." (PMID 33578611, 2021). "Frequently encountered alterations include MDM2 amplification for well-/dedifferentiated liposarcomas, MYC amplification for radiation induced angiosarcoma or segmental chromosomal deletions on chromosome 22q encompassing SMARCB1 for rhabdoid tumours." (PMID 33479225, 2021). "APG-115, another small molecule MDM2 inhibitor, was tested in a phase I study of 21 patients with liposarcomas and other solid tumors, including one with OS." (PMID 34503094, 2021). "The surgical material also showed MDM2 gene amplification, which is used for standard differential diagnosis of dedifferentiated liposarcoma." (PMID 34768995, 2021). "Liposarcomas are characterized by amplification of MDM2, which mediates serine metabolism addiction, promoting nucleotide synthesis to sustain tumor growth." (PMID 33801846, 2021). "MDM2 and CDK4 were already familiar as important factors in the pathological diagnosis of liposarcoma, but as MDM2- or CDK4-targeted drugs were investigated, their efficacies against STS (especially liposarcomas) were also evaluated." (PMID 31963219, 2020). "While MDM2 amplification in such tumors usually supports a diagnosis of dedifferentiated liposarcoma, HGESS‐BCOR should also be considered in the differential diagnoses in such cases." (PMID 32352245, 2020). "In 26 cases, MDM2 FISH helped to confirm the diagnosis of liposarcoma, with 16 WDL and 10 cases of DDL, all of which were intra-abdominal." (PMID 33061792, 2020). "Dedifferentiated liposarcomas have genetic abnormalities with high-level amplification of chromosome 12q14–15, which includes the MDM2 and CDK4 cell cycle oncogenes." (PMID 32611426, 2020). "Amplification of MDM2 was detected most frequently (1.4%; 3 lung cancer, 1 melanoma, 2 liposarcoma, 2 urothelial carcinoma samples), which is reported to be associated with hyperprogressive disease after immunotherapy treatment." (PMID 32264863, 2020). "Five translocations out of the 10 fusion-positive samples confirmed by tissue sequencing were detected in the corresponding cfDNA, as well as MDM2 amplification in a case of MDM2-amplified liposarcoma." (PMID 33287361, 2020). "Specifically, amplification of MDM2, which characterises both well‐differentiated and dedifferentiated liposarcoma and parosteal osteosarcoma and is routinely detected by FISH, were not called by the Canvas algorithm for copy number variant calling." (PMID 32573957, 2020).
liposarcoma (continued). "Fluorescence In suit Hybridization (FISH) test confirmed that the tumor was MDM2 gene positive, which clarified the diagnosis as well-differentiated mediastinal liposarcoma." (PMID 31387607, 2019). "The nutlin analogue RG7112 was the first MDM2 inhibitor tested in clinic in liposarcoma patients with MDM2 amplification." (PMID 31310659, 2019). "The authors found that co-overexpression of MDM2 and CDK4 causes high-grade sarcoma with a dedifferentiated liposarcoma-like morphology." (PMID 31160689, 2019). "MI-773 (SAR405838) significantly decreased the tumorigenecity of de-differentiated liposarcoma xenografts with high levels of MDM2." (PMID 31310659, 2019). "The observed partial response and prolonged progression-free survival provide an incentive for further study of MDM2 inhibitors in liposarcoma." (PMID 31310659, 2019). "Chest CT scan and MRI can help clarify the diagnosis, and molecular pathological examination of the MDM2, CDK4 and p16 gene in tumors provides the diagnostic gold standard in distinguishing well-differentiated liposarcoma from lipoma." (PMID 31387607, 2019). "This has been confirmed in a clinical context, during Phase I clinical studies with MDM2 inhibitor MI-773 in patients with liposarcoma." (PMID 31310659, 2019). "Molecular pathological examination of the MDM2, CDK4 and p16 gene in tumors provides the diagnostic gold standard in distinguishing well-differentiated liposarcoma from lipoma." (PMID 31387607, 2019). "The accuracy of separating CSCs can be further improved by adding other selection windows, such as CD99 for Ewing sarcoma or MDM2 for liposarcoma." (PMID 31882696, 2019). "Amplification and overexpression of MDM2 and CDK4 are well-known diagnostic criteria for well-differentiated liposarcoma (WDLPS)/dedifferentiated liposarcoma (DDLPS)." (PMID 31160689, 2019). "It is known that virtually all WD and DD liposarcomas have MDM2 amplification and close to 90% have CDK4 amplification and this is felt to be an early event in the pathogenesis of these tumors." (PMID 29731991, 2018). "Specifically, hMSCs that differentiated towards adipocytes or osteoblasts harbor CDK4 and MDM2 amplifications both of which frequently occur in osteosarcoma and liposarcoma that are both of same cell origin." (PMID 29416732, 2018). "MDM2 amplification was most frequent in patients with liposarcoma, followed by patients with metastatic breast cancer." (PMID 30237864, 2018). "Certain sarcomas, specifically liposarcomas, represent particularly promising cancer entities for treatment with MDM2 antagonists." (PMID 30206211, 2018). "A previous report is in seeming contradiction with our findings, claiming that Palbociclib cooperates with the MDM2 antagonist Idasanutlin (RG-7388) in killing liposarcoma cells." (PMID 30206211, 2018). "When c-Jun is amplified in dedifferentiated liposarcoma, it is interspersed with amplified MDM2 on ring and giant marker chromosomes suggesting that c-Jun is amplified at a similar time in the evolution of the tumor." (PMID 29731991, 2018). "Of the 13 sarcoma cases with MDM2 amplification, liposarcoma was the most common histologic subtype (9 patients)." (PMID 30237864, 2018). "Immunohistochemistry for CDK4, MDM2, and p16 expression aids in the differential diagnosis of well-differentiated and dedifferentiated liposarcoma from other adipocytic neoplasms." (PMID 28856628, 2017).
liposarcoma (continued). "Clinical trials are underway in liposarcoma using MDM2 inhibitors either singly or in combination with CDK4 inhibitors." (PMID 28424409, 2017). "Regarding liposarcomas, MDM2 gene amplification and CHOP gene rearrangement are useful to sub classify liposarcomas, and can be utilized to differentiate certain subtypes of liposarcomas from benign lipomas." (PMID 29531545, 2017). "Data were collected from the phase I trial (NCT01636479) with patients affected by de-differentiated/MDM2 amplified liposarcoma under SAR405838 treatment." (PMID 28673313, 2017). "Well-differentiated/dedifferentiated liposarcoma (WDLPS/DDLPS) are characterized by a consistent amplification of the MDM2 gene." (PMID 28903316, 2017). "This has previously been observed in dedifferentiated liposarcoma and even found to be co-expressed with MDM2 and CDK4." (PMID 28424409, 2017). "The first published results on the clinical potential of RG7112 have been obtained in a trial of the European Community (EudraCT number: 2009-015522-10) investigating the pharmacodynamics of RG7112 in patients with MDM2-amplified liposarcoma." (PMID 28673313, 2017). "Ten of these co-amplified CDK4/MDM2 cases were dedifferentiated liposarcomas, seven were well-differentiated liposarcomas, two rhabdomyosarcomas (one pleomorphic and one nos), one osteosarcoma, one ewing sarcoma, and one unclassified soft tissue sarcoma." (PMID 28424409, 2017). "Well-differentiated and dedifferentiated liposarcomas have 12q13-15 amplification resulting in MDM2 overexpression." (PMID 27893412, 2017). "Five of these were found to be grade 1 liposarcomas with normal histology but with cytogenetic analysis confirming MDM2 amplification." (PMID 27277260, 2017). "Four of the well-differentiated liposarcoma patients were treated with an investigational MDM2 inhibitor and all achieved at least stable disease, some showing a very durable response." (PMID 28424409, 2017). "The FISH technique was used to analyze 17 specimens of liposarcoma for MDM2 amplification and CHOP rearrangement, and 10 specimens of synovial sarcoma for SYT rearrangement." (PMID 29531545, 2017). "Amplification of cyclin-dependent kinase 4 (CDK4) and murine double minute 2 (MDM2) occurs in well-differentiated and dedifferentiated liposarcomas, as does down-regulation of PTEN." (PMID 28459858, 2017). "Initial clinical trials that utilize MDM2 PPIs have reported evidence of therapeutic responses in relapsed leukemia and liposarcoma." (PMID 29065514, 2017). "FISH was performed on 17 liposarcoma and 10 synovial sarcoma tumors with commercially available probes for MDM2 amplification and CHOP and SYT rearrangements." (PMID 29531545, 2017). "Several works described MDM2 amplification in 7% human solid tumor, such as liposarcoma (50%–90%), osteosarcomas (16%), esophageal carcinomas (13%), and NSCLC (6%)." (PMID 28124991, 2017). "Of particular interest, CPM (carboxypeptidase M) - located at the edge of the 12q amplicon, outside of what was thought to be the key region defined by CDK4 and MDM2 - was amplified in 39 of 50 well- and de-differentiated liposarcomas." (PMID 27732970, 2017). "Well-differentiated liposarcoma (WDLPS) and dedifferentiated liposarcoma (DDLPS) are closely related tumors commonly characterized by MDM2/CDK4 gene amplification, and lack clinically effective treatment options when inoperable." (PMID 28099935, 2017). "Re-examination of WD/DD liposarcoma demonstrates that, in fact, hyperchromatic and strongly MDM2-positive cells are found within TLS." (PMID 27376027, 2016).
liposarcoma (continued). "In a subset of liposarcomas the small subgroup of MDM2+/CDK4- tumors shows favorable prognostic features compared to MDM2+/CDK4+ tumors." (PMID 27662657, 2016). "There is also emerging evidence that the presence of MDM2 amplification in an otherwise undifferentiated sarcoma is strong evidence that the tumor has arisen from dedifferentiation of a liposarcoma." (PMID 26987706, 2016). "We present a case of low grade liposarcoma initially misdiagnosed as a fibrosing retroperitoneal pseudotumor and discuss the utility of MDM2 FISH in establishing a definitive tissue diagnosis." (PMID 26987706, 2016). "CDK4 is located on the band q13 of chromosome 12, and this region contains MDM2, which is often amplified together in a variety of sarcomas such as liposarcoma, and rhabdomyosarcoma." (PMID 26992220, 2016). "Further-more, Mdm2 antagonists appear most effective in tumors that contain amplifications of Mdm2, such as liposarcoma and osteosarcoma." (PMID 27688014, 2016). "The dedifferentiated liposarcoma can have prominent inflammatory myofibroblastic tumor-like features with expressions of MDM2 and CDK4 for identification." (PMID 25945274, 2015). "MDM2 is overexpressed in about 20% of STS including liposarcomas, synovial sarcomas, and leiomyosarcomas." (PMID 26427052, 2015). "The most evidence, to date, demonstrates an oncogenic role in dedifferentiated liposarcoma, like the atypical lipomatous tumor/well-differentiated liposarcoma, for MDM2, CDK4, HMGA2, and TSPAN31 (SAS)." (PMID 25713799, 2015). "These compounds are mostly tested in sarcoma patients, eg. well-differentiated and dedifferentiated liposarcomas, because MDM2 gene amplification occurs in about 20% of all cases, making them adequate study subjects." (PMID 26125230, 2015). "Our MDM2 Q-PCR analysis results also showed MDM2 amplification in 46 out of 48 cases in our liposarcoma specimens." (PMID 25121597, 2014). "This work revealed massive highly focal amplifications throughout the aneuploid tumor genome including MDM2, a gene that has previously been found to be amplified in well-differentiated liposarcoma." (PMID 24505276, 2014). "Most karyotypically complex liposarcomas have amplification of the 12q14 chromosome region that includes MDM2 and CDK4 gene." (PMID 25238053, 2014). "Expression of STAT6 in ca. 10% of dedifferentiated liposarcomas is based on amplification of the corresponding gene located in proximity to MDM2 and CDK4." (PMID 25432794, 2014). "In recent reports, it has been shown that dedifferentiated liposarcoma can have prominent inflammatory myofibroblastic tumor-like features with expressions of MDM2 and CDK4 for identification." (PMID 25022487, 2014). "Genomic amplification of the Mouse double minute 2 homolog (MDM2) locus is characteristic for well differentiated and dedifferentiated liposarcomas." (PMID 25126005, 2014). "MDM2 is over-expressed in over 30% of sarcomas, 80% of well-differentiated liposarcomas (WDLPS), and 60% of myxoid liposarcomas." (PMID 24147044, 2013). "Recently, the identification and gene amplification of the MDM2 gene have been identified to supplement the pathological diagnosis of liposarcoma." (PMID 24385845, 2013).